SULF2 (sulfatase 2)
Diseases named in the same sentence as SULF2 in open-access papers (continued):
Sharing a sentence is not in itself a finding about the gene and the disease.
malignant glioma (1 paper, 2015). A grade III or grade IV glioma arising from the central nervous system. "Furthermore, the ablation of SULF2 decreases tumor growth, prolongs host survival and decreases the activity of PDGFRα, as well as related downstream signaling pathways in human and mouse malignant gliomas." (PMID 26248280, 2015).
melanoma (1 paper, 2024). A malignant, usually aggressive tumor composed of atypical, neoplastic melanocytes. "A375 TFCP2 knockout human melanoma cells have decreased expression of HS3ST3A1 and HS6ST2 and increased expression of SULF1 and SULF2 what allowed the authors to state TFCP2 as a novel transcriptional regulator of HS biosynthesis." (PMID 39318629, 2024).
relapsing-remitting multiple sclerosis (1 paper, 2024). The most common clinical variant of multiple sclerosis, characterized by recurrent acute exacerbations of neurologic dysfunction followed by partial or complete recovery. "However, IFNβ signaling can also suppress auto-immune responses, such as in relapsing remitting multiple sclerosis, where IFNβ is used therapeutically to slow disease progression, and Sulf2 may have deleterious effects in such contexts." (PMID 39141086, 2024).
Sepsis (1 paper, 2021). Sepsis is defined as life-threatening organ dysfunction caused by a dysregulated host response to infection. "AKT1, top up- (FKBP5, SORT1, VNN1, and CST7) and downregulated (PRR5L, SH2B3, SULF2, PLEKHO1, and PTPN6) genes in sepsis were validated using RT-PCR." (PMID 33959663, 2021).
testicular cancer (1 paper, 2011). A primary or metastatic malignant neoplasm that affects the testis. "Finally, SULF1 and SULF2 were simultaneously overexpressed in 6 cancer types: brain, breast, head and neck, renal, skin and testicular cancers." (PMID 21599997, 2011).
Wilms tumor (1 paper, 2021). An embryonal neoplasm characterized by the presence of epithelial, mesenchymal, and blastema components. "Further support for the connection between SULF2/SULF1 and proteinuria was obtained from children with Wilms’ tumor." (PMID 33540508, 2021).
tumor (60 papers, 2006 to 2026). "SULF2-positive HCCs were typically larger and associated with extrahepatic disease, consequently with a more advanced tumour node metastasis stage." (PMID 36589727, 2022). "These heparan sulfate editing enzymes were considered largely functional redundant but single-cell RNAseq (scRNAseq) shows that SULF1 is secreted by cancer-associated fibroblasts in contrast to the SULF2 derived from tumor cells." (PMID 36428645, 2022). "Sulfatase 2 (SULF2) is elevated in HCC that is linked with increased tumor growth, hepatoblast phenotype, and a higher rate of tumor recurrence." (PMID 34754365, 2021). "Elevated expression of SULF2 was associated with vascular invasion and advanced tumor stage and shorter overall survival." (PMID 34249755, 2021). "The results suggest that SULF2 overexpression is associated with proliferative activity of tumor cells." (PMID 33585200, 2020). "Intriguingly, after adjusting for age, sex, race, histologic type, stage, and neoadjuvant therapy, tumor cell staining for SULF2 was associated with a trend towards increased risk of death (31%, NS) in ADC patients." (PMID 26882224, 2016). "Conversely in patients with SCC, SULF2 staining in tumor cells was associated with a significantly decreased risk of death (89%, p = 0.02)." (PMID 26882224, 2016). "In all patients, presence of SULF2 staining of either tumor cells or stroma was associated with a 42% increase in the risk of death, but this result was not statistically significant (p = 0.39)." (PMID 26882224, 2016). "After adjusting for age, sex, race, histologic type, stage, and neoadjuvant therapy, there was a non-significant (31%; p = 0.65) increase in the risk of death for patients with adenocarcinoma with SULF2 staining in tumor cells." (PMID 26882224, 2016). "An overview of SULF gene expression in human cancers indicates that although SULF1 is sometimes downregulated, more often SULF1 and/or SULF2 are overexpressed in tumours, which can be associated with a worse prognosis." (PMID 25681501, 2015). "SULF1 has been associated with tumor suppressor effects in various models of cancer, whereas SULF2 dysregulation was in relation with protumorigenic actions." (PMID 21599997, 2011). "To further evaluate the association between SULF2 expression and aggressiveness of tumor cells, we performed immunohistochemical staining of Ki67, a cell proliferation marker, in 40 patient samples and we evaluated the distribution of Ki67 in tumor cells." (PMID 33585200, 2020). "In addition, SULF2 protein measured by IHC follows similar expression/survival trends and is associated with higher proliferative activity of tumor cells measured by IHC staining of Ki67." (PMID 33585200, 2020). "Using data mining from published transcriptomic datasets of UBUCs (GSE31684 and GSE32894), SULF1 and SULF2 were identified as significant genes showing upregulation during tumor progression among those associated with the heparan sulfate proteoglycan metabolic process (GO:0030201)." (PMID 28525382, 2017). "After adjusting for age, sex, race, histologic type, stage, and neoadjuvant therapy, patients with ADC with SULF2 staining in tumor cells had a 31% increased risk of death (p = 0.65), and patients with SCC with SULF2 staining in tumor cells had an 89% decreased risk of death (p = 0.02)." (PMID 26882224, 2016). "In fact, SULF2 is involved in Wnt-driven tumor progression, PLAUR in extracellular matrix remodeling and migration, DUSP4 in sustaining epithelial–mesenchymal plasticity, and ATP6V0A4/V-ATPase-dependent acidification in invasive phenotypes." (PMID 41596301, 2026). "The fact that they are produced by different cell types suggests that the SULF1 will regulate the local microenvironment of the CAF more than the SULF2 which will be active closer to the tumor cells." (PMID 41549062, 2026). "It is interesting to note that the SULF2 KO in the Cal33 cancer cells also limits tumor cell growth and limits cell invasion." (PMID 41549062, 2026).
tumor (continued). "SULF2 is upregulated in human CCA and is associated with enhanced PDGFRβ-YAP signalling, tumour progression and chemoresistance." (PMID 38332153, 2024). "Although we did not detect LINC00313 over-expression in CCA tissues, the expression levels of ACTL6A, TCF7, WNT5A, AXIN2 and SULF2 were all increased in CCA human tumours (Fig. EV5B)." (PMID 38332153, 2024). "Sulf-2 is secreted in the tumor tissues primarily by cancer cells while Sulf-1 is supplied to the tumor microenvironment by CAF cells." (PMID 38825040, 2024). "Human heparan sulfatase-2 (HSULF-2) is an oncoprotein overexpressed in the surface of all types of tumor cells and its activity plays a critical role in cancer survival and progression." (PMID 36644581, 2023). "Meanwhile, EDNRA, PRRX1, EMP1, AKR1B1, and SULF2 exerted an important role in cancer progression in other tumor types." (PMID 36816947, 2023). "This suggests that the secreted Sulf-2 enzyme remodels the cell–cell and cell–matrix interactions in as yet undefined ways that affect the invasion of the tumor cells into the matrix." (PMID 37958342, 2023). "Sulf-1 is supplied to the tumors primarily by the CAF, while Sulf-2 is more abundant in the epithelial HNSCC tumor cells." (PMID 37958342, 2023). "The demonstrated inhibition of HS biosynthetic system was mainly due to the selective significant suppression of the N-deacetylase/N-sulfotransferases Ndst1 and Ndst2 and sulfatase Sulf2 (-3–3.5-fold) in the tumor tissues." (PMID 37373391, 2023). "This is consistent with the reduced expression of SULF2 mRNA in tumor tissues of LIHC (log2FC = −0.481, FDR = 0.116) and UCEC (log2FC = −1.76, FDR < 0.001)." (PMID 36428645, 2022). "Whereas SULF-2 plays tumor-promoting roles in several cancer types by supporting the signaling of HS-binding growth factors, SULF-1 is generally considered an onco-suppressor albeit an oncogenic role in hepatocarcinogenesis has been reported." (PMID 36359323, 2022). "SULF1 is associated with poor survival in univariate analysis but, contrary to SULF2, loses a significant impact when analyzed in a multivariable model together with SULF2, age, gender, smoking history, tumor stage, and radiation therapy." (PMID 36428645, 2022). "SULF2 derived from CAFs modulates glypican-3/β-catenin signalling but also the HCC immune TME, associated with tumour progression and therapy resistance via activation of the TAK1/IKKβ/NF-κB pathway." (PMID 36589727, 2022). "The in situ hybridization clearly shows that SULF1-expressing cells are more common in the stroma (mean 24.9% stroma vs. 8.4% tumor, p < 0.001) while SULF2 expression is higher in the cancer cells (mean 22.7% stroma vs. 52.5% tumor, p < 0.001)." (PMID 36428645, 2022). "SULF2 is expressed in 63% of all tumor cells (n = 1389 of 2215) which is the highest representation among all the cell types." (PMID 36428645, 2022). "We have shown that SULF1 and SULF2 enzymes increase in tumor tissues of patients with HNSC and that the increase is associated with poor survival." (PMID 36428645, 2022). "This study elucidates the effect of SULF2 on the polarization of macrophages in the tumor microenvironment." (PMID 36612128, 2022). "SULF1 expression is significantly higher in fibroblasts compared with tumor epithelial cells in terms of both percent positivity and expression; in contrast, SULF2 expression has the opposite trend." (PMID 36428645, 2022). "In tumour tissues, SULF2 was overexpressed in 58% (35/60) of HCC cases, corroborating previously reported gene expression data." (PMID 36589727, 2022). "In human HCC tissues, CAF-SULF2 was associated with increased macrophage recruitment, with tumouroid studies showing stromal-derived SULF2-induced paracrine activation of the IKKβ/NF-κB pathway, tumour cell proliferation, invasion, and sorafenib resistance." (PMID 36589727, 2022).
tumor (continued). "The mean SULF1 mRNA, represented as log2(TPM+1), is 0.172 in tumor cells compared with 1.099 in fibroblasts (p < 0.001); the mean value of SULF2 mRNA is 1.145 in tumor cells compared with 0.386 in fibroblasts (p < 0.001)." (PMID 36428645, 2022). "IVIS showed that knockdown of SULF2 expression significantly inhibited the size and number of tumor metastases while overexpression of SULF2 promoted tumor metastasis." (PMID 36612128, 2022). "Presently, studies have indicated that SULF2 is a potential tumor driver gene for cholangiocarcinoma and glioblastoma." (PMID 36612128, 2022). "To further strengthen the observation that SULF1 is expressed in fibroblasts and SULF2 in tumor cells, we analyzed the RNA-seq data from the Cancer Cell Line Encyclopedia (CCLE)." (PMID 36428645, 2022). "In our patient series, nuclear localization of RelA-P-ser536 in tumour cells was a dramatic feature in HCC biopsies with high levels of SULF2." (PMID 36589727, 2022). "In our biopsy cases, the tumour cells were the source of elevated SULF2 in only 15% (9/60), where SULF2 was detected in the tumour cell cytoplasm and/or membrane." (PMID 36589727, 2022). "Collectively, these data indicate that SULF2 reveals a new way for tumor immune escape during BCa progression." (PMID 36612128, 2022). "SULF2 also can modulate the expression of cell surface signal molecules on tumor cells by regulating the sulfation of the glycosyl part of HSPGs." (PMID 36612128, 2022). "Briefly, 60% of patients had more than 25%-positive SULF2 cells and the higher level of SULF2 was correlated with tumor stage, perineural invasion and vascular invasion." (PMID 34249755, 2021). "SULF1 and SULF2 act at the interface between tumor cells and their microenvironment, taking part in key interactions between local tumor and host cell interactions." (PMID 34249755, 2021). "Previous studies have demonstrated that tumor cells secreted increased amounts of SULF2 in the HCC microenvironment." (PMID 33889573, 2021). "The expression of SULF1 and SULF2 enzymes is differently regulated in a number of tumors, but their precise role in tumor growth has remained controversial." (PMID 34249755, 2021). "We observed that both SULF1 and SULF2 are significantly upregulated in HNSCC tumor with 5.1-fold and 2.2-fold increase compared to adjacent benign tissues, respectively (both p < 0.001, paired t-test)." (PMID 33585200, 2020). "We found a significant overexpression of SULF2 in HNSCC tumor tissues which differs by tumor location and etiology." (PMID 33585200, 2020). "Further exploration of gene expression in FFPE tumor sections from HNSCC patients revealed that EXT1 is significantly elevated in SULF2-positive tumor tissues." (PMID 33585200, 2020). "Both SULF1 and SULF2 expression in tumor samples showed significant differences among the four locations (p = 0.018 for SULF1, p < 0.001 for SULF2, one-way ANOVA)." (PMID 33585200, 2020). "We find that SULF2 staining is significantly higher in tumor samples with high Ki67 staining (p < 0.001, n = 40)." (PMID 33585200, 2020). "The fold-change of SULF1 and SULF2 upregulation in tumor among these 43 patients are moderately correlated (Pearson’s r = 0.563, p < 0.001), as is the mRNA expression in tumor tissues in all 499 patients (r = 0.390, p < 0.001)." (PMID 33585200, 2020). "To further evaluate the biological impact of SULF2 expression in HNSCC tumor, we examined the sulfation in tumor sections by HS3A8 antibodies binding preferentially the 6-O-sulfate and by LC-MS/MS of HS disaccharides." (PMID 33585200, 2020). "We analyzed differential expression of both SULF1 and SULF2 in a group of 43 patients from the TCGA-HNSC with RNA-seq results of paired tumor and adjacent benign mucosal tissue." (PMID 33585200, 2020). "In this study, we found that SULF2 overexpression in HNSCC tumor tissues is consistently observed at both mRNA and protein levels, which further confirms our previous results." (PMID 33585200, 2020).
tumor (continued). "The reaction is carried out by two endosulfatases located on the cell surface, SULF1 and SULF2, and alterations in the expression of these genes in various tumor types, either up- or downregulation, have been reported." (PMID 29940912, 2018). "In a model of experimental animals, the correlation of SULF2 expression with PDGFRα phosphorylation and decreased MAPK signaling has been shown, whereas the knockout of Sulf2(−/−) resulted in an inhibition of tumour growth in experimental animals in vivo." (PMID 29104277, 2017). "The proportion of cells showing SULF2 staining was significantly higher (p-value = 0.0002) in HNSCC tumor tissue (mean = 0.98, SD = 1.00) compared to adjacent tissue (mean = 0.26, SD = 0.51)." (PMID 27223083, 2016). "The IHC analysis undertaken in this study showed a statistically significant increase in the expression of SULF2 in HNSCC tumor tissues compared to adjacent cancer-free tissue." (PMID 27223083, 2016). "Overall, we have shown that SULF2 is over-expressed in HNSCC tumor tissue and increases in intensity and distribution in late stage tumors." (PMID 27223083, 2016). "What is surprising is that despite their seemingly identical function, there are data to support the conclusion that Sulf-1 suppresses tumour growth while Sulf-2 promotes tumour growth." (PMID 27408707, 2016). "This treatment promoted the entry of tumor cells into the blood stream (intravasation), which was abolished by downregulating SULF2 expression in tumor cells." (PMID 26895473, 2016). "SULF2 staining in either tumor or stromal cells was detected on 72/93 of the specimens, including 25/42 (60%) of ADC samples and 51/51 (100%) of SCC samples." (PMID 26882224, 2016). "Given the clear increase of SULF2 in tumor tissue and its secreted nature, SULF2 in the serum of HNSCC patients was determined." (PMID 27223083, 2016). "We ascertained if SULF2 expression was affected by tumor properties or characteristics of the patients." (PMID 27223083, 2016). "SULF2 expression in the tissue was unaffected by patient demographics, tumor location or etiological factors including smoking and HPV infection." (PMID 27223083, 2016). "Due to the proximity to the tumor location, SULF2 was then evaluated in mouthwash samples available for a subset of patients." (PMID 27223083, 2016). "We also assessed the effect of OKN-007 regarding the immunoexpression of tumor signaling molecules such as PDGFRα, SULF2, and decorin in the IC-3752GBM pGBM model." (PMID 26248280, 2015). "Overall, it is conceivable to conclude that Sulf1 plays anti-tumor roles whereas Sulf2 plays tumor-promoting roles in several tumor types." (PMID 25105093, 2014). "Heparanase, Sulf1, and Sulf2 drive a range of processes in the tumor microenvironment, many of which, in the case of heparanase and Sulf2 promote tumor malignancy, and some, in the case of Sulf1 inhibit malignancy." (PMID 25105093, 2014). "OKN-007 effectively inhibited tumor growth in HCC derived tumor xenografts exhibiting Sulf2 expression." (PMID 25105093, 2014). "Inmunostaining and CISH techniques applied for SULF1 and SULF2 respectively corroborated this data, showing stronger staining in tumor cells relative to healthy ones." (PMID 23327652, 2013). "On the other hand, Sulf2 has been shown to be proangiogenic, and depletion of this enzyme leads to reduced tumor size." (PMID 23984412, 2013). "The different expression levels and methylation status of SULF2 between tumor and normal tissue also need to be further verified." (PMID 24124496, 2013). "It has been shown that the two isoforms Sulf1 and Sulf2 seem to present different activities during tumor growth." (PMID 23984412, 2013). "For instance, structurally similar heparin-degrading endosulfatases sulfatase 1 (SULF1) and sulfatase 2 (SULF2) have been reported recently as having a role of a tumor suppressor and oncogene, respectively, in HCC by regulating different signaling pathways." (PMID 22973521, 2012).